IL10 (interleukin 10)
Diseases named in the same sentence as IL10 in open-access papers (continued):
Sharing a sentence is not in itself a finding about the gene and the disease.
Insulin resistance (continued). "Several parameters including blood glucose, lipid profile, CRP, TNF-α, IL-10, and insulin resistance (IR) were measured over the whole study period." (PMID 35096939, 2021). "Bregs restrict adipose tissue inflammation and insulin resistance in obese mice in an IL-10 dependent manner." (PMID 35822048, 2021). "Germline deletion of IL-10 protects mice from insulin resistance and diet-induced obesity (DIO), by increasing Ucp1, PR/SET domain 16 (PRDM16), and other thermogenic genes in adipocytes in the white adipose tissue (WAT)." (PMID 33351782, 2021). "Although previously shown to be required for suppression of adipose tissue inflammation and insulin resistance, a recent study showed that IL-10 can directly suppress thermogenesis in adipocytes through a STAT3-dependent signaling pathway." (PMID 33351782, 2021). "In particular, T2DM are often characterized by insulin resistance due to low production or impaired signaling cascade of IL-10 concomitant to enhanced expression of pro-inflammatory molecules." (PMID 33858419, 2021). "It has been reported that Il10 plays a potent role in adipocyte differentiation and insulin resistance." (PMID 33303977, 2021). "For example, infusion of adipose tissue-derived stem cells (ADSCs) reduces hyperglycemia and insulin resistance in diabetic rats, a response dependent on spleen-derived IL10 expression." (PMID 34248663, 2021). "IL-10 germline deficient mice were significantly protected from DIO, weight gain, and correspondingly, insulin resistance and glucose intolerance." (PMID 33351782, 2021). "IL-10 is a protective factor against diet-induced insulin resistance in the liver and in skeletal muscle as it attenuates macrophage cytokine secretion." (PMID 35822048, 2021). "Inside VAT, a subset of these Bregs are maintained by CXCL12 and free fatty acids and Breg deletion of IL-10 results in aggravated VAT inflammation, insulin resistance, and loss of metabolic homeostasis." (PMID 32499756, 2020). "In contrast, M2 macrophages secrete anti-inflammatory cytokines, such as IL-10, which suppress inflammation and have a positive effect on improving insulin resistance." (PMID 33298044, 2020). "For instance, the anti-inflammatory cytokine IL10 prevents TNFα-induced insulin resistance in adipocytes." (PMID 32408016, 2020). "In contrast, M2 macrophages secrete anti-inflammatory factors, such as IL-10, which suppress inflammation and have a positive effect on improving insulin resistance." (PMID 33298044, 2020). "Specifically, IL-10 regulates insulin resistance and hyperglycemia as an effective anti-inflammatory cytokine." (PMID 32425787, 2020). "Further, to validate the functional impacts of the rs35652124 TT genotype on insulin resistance and wound healing process, we have studied the transcriptional profile of IL-10, TNF-α, and IL-6 in the study cohort based on their genotype." (PMID 32879654, 2020). "In summary, we reported a novel connection between IL-10 rs3021094 SNP with GDM incidence, IL-10 level, and insulin resistance were also in significant correlation." (PMID 30873205, 2019). "In the insulin resistance control group, the expression levels of IL-6, RORγt, and IL-17 increased, whereas those of IL-10, FoxP3, and CD4+CD25+Treg decreased." (PMID 31218568, 2019). "Specifically, an increased density of the IL10 and TNFα-secreting CD11C+CD206+ ATMs in adipose tissue was associated with insulin resistance, which coincides with the observed increase of M-IL10 and M-LPSearly signals while the M-IL4 signal remained unaltered." (PMID 31921150, 2019). "Plasma IL-10 can prevent insulin resistance, and the level of blood glucose in the blood is constantly changing." (PMID 32038285, 2019). "As an efficient anti-inflammatory cytokine, IL-10 can improve hyperglycemia, and insulin resistance." (PMID 31134090, 2019).
Insulin resistance (continued). "As the blood glucose level decreases after fasting, and the role of IL-10 in preventing diet-induced insulin resistance weakens, the IL-10 level is low." (PMID 32038285, 2019). "As an inhibitor of TNF-α expression, IL-10 is recognized as an efficient anti-inflammatory cytokine, which can ameliorate insulin resistance and hyperglycemia." (PMID 30186548, 2018). "IL10 has been shown to be able to ameliorate inflammation in obese adipose tissue and insulin resistance induced by proinflammatory cytokines, TNF-α and MCP-152,53." (PMID 29545532, 2018). "Remarkably, B-1a-cell transfusion protects against insulin resistance through IL-10 and polyclonal IgM mechanism." (PMID 28491871, 2017). "Some studies have proposed a protective role for IL-10 in diabetic retinopathy and a mouse model of diet-induced insulin resistance." (PMID 28841856, 2017). "Conversely, B cells have also been reported to play important roles in inhibiting inflammation and insulin resistance by IL-10 or/and polyclonal IgM mechanism." (PMID 28491871, 2017). "Blood samples were collected over the 14-week study and analyzed for glucose, lipid profile, and CRP, lipid particles, TNF-α, IL-10, insulin, and insulin resistance (IR)." (PMID 29410955, 2017). "The macrophages in adipose cells secrete proinflammatory cytokines (adipocytokines) such as C-reactive protein, interleukin (IL)–6, IL-8, IL-10, and tumor necrosis factor–α; these cytokines impair insulin signaling, inducing insulin resistance." (PMID 28234943, 2017). "High IL-10 levels, for example, have been reported to promote insulin sensitivity in humans and protect against insulin resistance by diminishing TNF mediated intracellular signaling in adipocytes." (PMID 27239103, 2016). "On the other hand, expansion of Treg cell contingent in high-fat-diet-fed mice and increased secretion of IL-10 led to a significant reduction of blood glucose levels, insulin resistance, and glucose tolerance." (PMID 25759691, 2015). "Conversely, obese B null mice lack inflammatory cytokines, produce high levels of IL-10, and are protected against insulin resistance." (PMID 25759691, 2015). "Obese B cell null mice had decreased inflammatory cytokines, including IL-6 and IFN-γ, increased anti-inflammatory IL-10 levels, and protection against insulin resistance compared to obese wildtype mice." (PMID 25157251, 2014). "This study also showed that interleukin-10 (IL-10), produced by these Foxp3 Treg cells, inhibited tumor necrosis factor-alpha (TNFα)-induced expression of proinflammatory mediators and insulin resistance in 3T3-L1 adipocytes." (PMID 23671849, 2013). "In the context of insulin action, M2 macrophages sustain insulin sensitivity by secreting IL-4 and IL-10, while M1 macrophages induce insulin resistance through the secretion of proinflammatory cytokines, such as TNFα." (PMID 23964268, 2013). "IL-10 secreted by M2 macrophages enhances insulin signaling, including that in the liver, thereby having a protective role against obesity-induced insulin resistance." (PMID 23964268, 2013). "Clinical significance of circulating IL10 concentrations have been demonstrated in acute coronary syndrome and insulin resistance." (PMID 23941335, 2013). "Plasma levels of the anti-inflammatory cytokine IL-10 have been found to positively correlate with insulin sensitivity and IL-10 treatment protects against diet-induced insulin resistance." (PMID 22470484, 2012). "Hyperinsulinemic-euglycemic clamp studies showed that IL-10 prevents IL-6-induced insulin resistance in the liver and the skeletal muscle in mice." (PMID 22051061, 2011). "Furthermore, overexpression of IL‐10 in the muscle of transgenic mice protects against diet‐induced insulin resistance and inflammation." (PMID 40903907, 2025).
Insulin resistance (continued). "Laurate-bioconjugated fructans reduced food and energy intake, body weight, body mass index, abdominal circumference, adipose tissue, adipocyte area, serum triglycerides, insulin, insulin resistance, and C-reactive protein but they increased IL-10 protein serum levels and mRNA expression." (PMID 39204141, 2024). "In addition, insulin resistance and glucose intolerance are observed in mice with liver-specific IL-6Rα KO, resulting in increased IL-6, IL-10, and TNF-α expression." (PMID 38999780, 2024). "Our data clearly demonstrated that IL-10-treated adipose stromal cells could be used to alleviate liver glucose gluconeogenesis, insulin resistance, and DPP4 activity in a mouse model of T2DM." (PMID 39125659, 2024). "Additionally, elevated levels of IL-1β have been proved to promote insulin resistance and liver inflammation, whereas IL-10 has the opposite effect." (PMID 38302976, 2024). "In the future, the injection of IL-10-treated adipose stromal cells could be a novel and promising cell therapy strategy for alleviating insulin resistance, gluconeogenesis, and DPP4 activity in DM." (PMID 39125659, 2024). "Endogenous IL-10 protects against diet-induced insulin resistance in the liver." (PMID 39125659, 2024). "Our data clearly demonstrate that IL-10-treated adipose stromal vascular cells could be used as a novel cell therapy strategy to alleviate liver glucose gluconeogenesis and insulin resistance in T2DM." (PMID 39125659, 2024). "Endogenous interleukin-10 (IL-10) protects against diet-induced insulin resistance." (PMID 39125659, 2024). "In addition, blood glucose and insulin resistance decreased, while the antioxidant parameter, nuclear factor erythroid 2–related factor 2 (Nrf2) and interleukin 10 (IL10), and anti-inflammatory agent increased." (PMID 38775851, 2024). "There is a correlation between low IL-10 levels and excessive insulin resistance." (PMID 38068941, 2023). "It has been suggested that IL‐10 expression levels are decreased in nonalcoholic steatohepatitis (NASH) and the worsening of pro‐inflammatory markers and insulin resistance when neutralizing anti‐IL‐10 antibodies have been used in a diet‐induced mouse model of NAFLD." (PMID 36637998, 2023). "However, IL-10 derived from immune cells can suppress thermogenesis and energy expenditure in adipocytes that drive insulin resistance in obesity." (PMID 37833312, 2023). "Studies have shown that HP infection induces the release of pro-inflammatory cytokines such as tumor necrosis factor alpha, interferon gamma, interleukin (IL)-1, IL-6, IL-8, IL-10, IL-12, and C reactive protein and was shown to be involved in the pathogenesis of insulin resistance." (PMID 36699110, 2023). "Stress-related hyperglycemia is associated with increased morbidity and mortality in critical illness, and IL-10 treatment has been shown to attenuate and prevent insulin resistance, improve insulin signaling, and beneficially affect peripheral glucose metabolism." (PMID 36243830, 2022). "The developing inflammation accompanying the development of insulin resistance in cells may be a factor stimulating the increase in the expression of anti-inflammatory cytokines such as IL-10." (PMID 35205339, 2022). "Insulin resistance in macrophages thus might result in impaired IL-10 formation and thereby contribute to worsening systemic insulin resistance." (PMID 35955975, 2022). "Growing evidence has shown that low serum levels of IL-10 are closely correlated with insulin resistance, while elevating serum IL-10 levels via exogenous IL-10 administration promotes amelioration of insulin resistance by skewing macrophages to M2 in high-fat diets (HFD)-fed mice." (PMID 35313972, 2022). "Additionally, most studies supported a protective role of IL10 in the regulation of metabolic inflammation and insulin resistance." (PMID 35715850, 2022). "Moreover, IL-1β was related with insulin resistance, and IL-10 inversely correlated with neonatal BW." (PMID 35303833, 2022).
Insulin resistance (continued). "In addition, we demonstrated that ALA decreases levels of proinflammatory TNF-α but also increases the synthesis of anti-inflammatory IL-10 in the hypothalamus of insulin-resistant rats." (PMID 35391928, 2022). "Cytokine and hormone profiling indicated that IL-10 mediated secretion of adiponectin could be the most important mechanism by which LTBI can confer protection against insulin resistance." (PMID 35832818, 2022). "Moreover, IL-1β in GDM was related with glucose metabolism and insulin resistance, and IL-10 inversely correlated with neonatal birth weight." (PMID 35303833, 2022). "In 3T3-L1 IR cells, similar to the SAT-derived IR adipocytes, we observed approximately a 4.5-fold increase of the IL10 expression level in IR cells, compared to control cells after 48 h after induction insulin resistance (p = 0.014), and more than a twofold increase after 72 h (p = 0.001)." (PMID 35205339, 2022). "Indeed, serum concentrations of IL-10 have been found to be significantly reduced in obese subjects and correlated with hyperinsulinemia and insulin resistance." (PMID 35782930, 2022). "Besides, neutralization of IL-10 using antibodies exacerbates hepatic steatosis and insulin resistance in mice." (PMID 35165344, 2022). "Based on the results, we speculated that IL-10 probably contributed to the effect of UC-MSCs on insulin resistance in EAT." (PMID 35313972, 2022). "Accordingly, we postulated that UC-MSCs could polarize macrophages towards M2 to alleviate insulin resistance in WAT by upregulating IL-10 production in the spleen." (PMID 35313972, 2022). "Also, IL-10 is known to prevent age-related inflammation and insulin resistance, which adversely affect muscle." (PMID 35215448, 2022). "It has been also reported that the live multi-strain probiotics were more effective than the non-viable probiotic strains in in improving insulin resistance associated with intestinal microbiota alteration, butyrate production, and il-10 induction." (PMID 34504116, 2021). "For example, MAIT cells from obese patients produce more of the proinflammatory cytokine IL‐17, but less of the anti‐inflammatory cytokine IL‐10, which may contribute to the increased insulin resistance observed in these patients." (PMID 33332759, 2021). "Additionally, over-expression of interleukin-10 protected mice from diet-induced inflammation and insulin resistance in skeletal muscle." (PMID 34638990, 2021). "It suggests that, in the initial phase of the disease, IL-10 and IL-12 could be related to insulin resistance (1° hit)." (PMID 34447378, 2021). "The M1 phenotype is characterized as the pro-inflammatory state, as these macrophages secrete pro-inflammatory cytokines, while the M2 phenotype, an anti-inflammatory state, can protect against insulin resistance by secreting anti-inflammatory cytokines such as interleukin-10 (IL-10)." (PMID 32183037, 2020). "In fact, it has been reported that high IL-10 production capacity could confer protection against insulin resistance and T2D." (PMID 32626786, 2020). "Upregulation of miR-3473b gene expression and high-efficiency inhibition of macrophage activation increased serum anti-inflammatory cytokine IL-10 levels in diabetic rats and effectively improved insulin resistance and chronic inflammatory response in diabetic patients." (PMID 33456489, 2020). "Furthermore, the administration of IL-10 improved the insulin resistance after lipid infusion, increased the glucose uptake in isolated adipocytes and diminished the insulin resistance induced by TNF-α." (PMID 32824505, 2020). "Increased IL-10 levels and insulin resistance were also related to the genotype of rs3021094." (PMID 30873205, 2019). "Furthermore, our study also revealed an increased insulin resistance and IL-10 levels in A/A + A/C genotypes." (PMID 30873205, 2019).
Insulin resistance (continued). "We supposed that SHED administration via the tail vein downregulated the serum levels of IL-1 and TNF-α and upregulated those of IL-10 in DN rats, not only improving insulin resistance but also affecting the renal immune response through inflammatory cytokines." (PMID 31871464, 2019). "First, IL-10 is produced by a variety of immune cell types, including monocytes and macrophages, which are potent inhibitors of pro-inflammatory cytokines and chemokines, and can prevent diet-induced insulin resistance." (PMID 32038285, 2019). "Besides, recent data have suggested the protective role of IL-10 against inflammation in adipose tissue and insulin resistance." (PMID 30539027, 2018). "Another possibility is improved insulin resistance resulting from IL-10." (PMID 29445750, 2017). "In a related study, it has been shown that high-fructose diet lowered IL-10, but did not change TNFα levels; however, PPARβ/δ deficiency made the insulin resistance apparent, in association with increased inflammatory markers, in adipose tissue of mice." (PMID 27066503, 2016). "Similarly, IL-10 secreted by M2 macrophages enhances insulin signaling in the liver and skeletal muscle and protects against obesity-induced insulin resistance." (PMID 26197341, 2015). "Because the anti-inflammatory cytokine IL–10 protects against insulin resistance by inhibiting the action of IKK on pIRS–1 (Ser307), we consider the high levels of IL–10 found in OTR/down were important in maintaining pIRS–1 (Ser 307) levels even with high levels of pIKKalpha/beta." (PMID 26445495, 2015). "Thus, to further analyze the association of IL-10 with these parameters, a correlation analysis was performed between IL-10 and both insulin and insulin resistance." (PMID 25944984, 2015). "Thus, the main goal of this study was to examine serum levels of IL-10 (a cytokine with potent anti-inflammatory actions) in morbidly obese subjects and its possible association with the degree of OSA and insulin resistance." (PMID 25944984, 2015). "Besides being inversely associated with serum TNF-α and IL-12, decreased IL-10 levels were significantly related to increased AHI, hyperinsulinemia, and insulin resistance." (PMID 25944984, 2015). "Present results show that serum levels of the anti-inflammatory cytokine IL-10 are significantly reduced in morbidly obese subjects with obstructive sleep apnea and show a strong correlation with a systemic state of hyperinsulinemia and insulin resistance." (PMID 25944984, 2015). "Consistent with this previous study, our results show that hyperleptinemia is significantly associated with high serum levels of TNF-α and IL-12, as well as reduced concentrations of IL-10 in subjects with central obesity, hyperglycemia, increased insulin resistance, and hypertriglyceridemia." (PMID 23986664, 2013). "IL10 also plays a protective role against the development of insulin resistance." (PMID 23941335, 2013). "Furthermore, IL-10 overexpression in mice is able to prevent diet-induced insulin resistance, and indeed we see increased IL-10 expression in the ad-12/15-LO mice fed a high-fat diet with concomitant improvements in insulin sensitivity." (PMID 23326022, 2012). "Furthermore, the degree of insulin resistance, glucose intolerance, liver steatosis, and adipose and liver inflammatory marker expression (TNFα, IL-6, IL-10, IFN-γ, MCP-1, MIP1α) induced by high fat feeding in CD1d−/− were not different from WT." (PMID 21674035, 2011). "Moreover, HS-BG fiber fermentation produces compounds that restored permeability in disrupted epithelial cells, decreased inflammatory chemokines (CXCL10, MCP-1, and IL-8), and increased anti-inflammatory marker (IL-10), which could improve insulin resistance." (PMID 39064683, 2024). "This may suggest that low IL-10 concentrations contribute to insulin resistance in GDM patients." (PMID 38068941, 2023). "In vivo studies showed that IL-10 could prevent IL-6 or lipid-induced insulin resistance." (PMID 35154341, 2022).